BCL2 (BCL2 apoptosis regulator)
Diseases named in the same sentence as BCL2 in open-access papers (continued):
Sharing a sentence is not in itself a finding about the gene and the disease.
breast carcinoma (continued). "This study is the first meta-analysis to assess the use of Bcl-2 expression for predicting the chemo-sensitivity of breast cancer patients." (PMID 24370277, 2013). "We have demonstrated that by regulating the Bax and Bcl-2 proteins, embelin induces the release of cytochrome C and activates the caspase family to induce the apoptosis of breast cancer cells." (PMID 23425971, 2013). "This method based on MOMP is a useful screening tool for identifying BH3 mimetics with selective toxicity against breast cancer cell mitochondria protected by the three major Bcl-2 anti-apoptotic proteins." (PMID 23705845, 2013). "The inhibition of STAT3 by LLL12 also down-regulated the expression of known STAT3 target genes in ALDH+ breast cancer cells related to cancer cell proliferation, survival, and angiogenesis, including Cyclin D1, survivin, Bcl-2, Bcl-XL, MMP-2, and MMP-9." (PMID 24376586, 2013). "CDAK induced apoptosis, reduced mitochondrial membrane potential, promoted Caspase-3, and inhibited Bcl-2 expression in the two breast cancer cell lines." (PMID 23326440, 2013). "It was reported to be down-regulated in breast cancer, partially due to DNA methylation, is known to directly target BCL2 and modulate drug resistance." (PMID 23405235, 2013). "The expression level of Bcl-2 in breast cancer and colon cancer are positively related with the survival time of the patient, that is to say, Bcl-2 is a positive factor for cancer patients." (PMID 23305095, 2013). "Decreased bcl-2 expression was observed in several cancer cell types treated with tamoxifen and daidzein and in equol-induced apoptosis in mammary carcinomas." (PMID 23675643, 2013). "We therefore performed a meta-analysis of the value of Bcl-2 expression for predicting sensitivity to chemotherapy in breast cancer." (PMID 24370277, 2013). "Several members of the proteins that control apoptosis, including the anti-apoptotic protein Bcl2 and the pro-apoptotic protein Bax are expressed in breast carcinoma." (PMID 24124558, 2013). "Bcl2 is an anti-apoptotic protein which is significantly more often expressed in male breast cancer compared to FBC." (PMID 23573235, 2013). "Although there have been many attempts to correlate Bcl-2 status with chemosensitivity in breast cancer patients, the results have been controversial." (PMID 24370277, 2013). "In panel E images of bcl-2 expression of CTC is shown: on top two CTC of a breast cancer patient are shown, one of them expressing bcl-2 whereas the other does not." (PMID 24305653, 2013). "TSA and vorinostat have been shown to induce apoptosis through a BCL-2/caspase-3-dependent mechanism in a number of cell types including mammary carcinomas, retinoblastoma, and leukemic T cells." (PMID 23667527, 2013). "PTEN loss and expression of c-Kit, c-Met, HIF-1α, PDGFRA VEGFR2, and VEGF-A have been reported to be worse prognostic factors for breast cancer, whereas expression of IGF-1R, Bcl-2 and survivin are reportedly good prognostic factors for breast cancer." (PMID 24245483, 2013). "Third, eugenol down-regulated several onco-proteins known to be highly expressed in breast cancer cells and tissues, such as NF-κB, β-catenin, cyclin D1, Bcl-2 and survivin." (PMID 24330704, 2013). "Pathway analysis also showed that miRNA-30a-3p was positively correlated with BCL2-mediated cellular survival/ceramide-induced apoptosis, which corresponded with a favorable role for increased BCL2 expression in breast cancer treated with endocrine therapy." (PMID 24137320, 2013). "In summary, our study has demonstrated that embelin releases cytochrome C and activates the caspase family to result in the induction of breast cancer apoptosis through regulation of the action of the Bcl-2/Bax family in the mitochondrial pathway." (PMID 23425971, 2013). "The results of the present meta-analysis suggest that Bcl-2 expression is a predictive factor for chemotherapy sensitivity in breast cancer patients." (PMID 24370277, 2013).
breast carcinoma (continued). "BTG1 is a Bcl-2-regulated mediator of apoptosis and contributes to antisense Bcl-2-mediated cytotoxic effects in breast cancer cells." (PMID 24084718, 2013). "In MCF-7 breast cancer cells miR-24 targets pro-survival protein Bcl-2 leading to increased sensitivity to apoptotic stimuli." (PMID 23383180, 2013). "It has been determined that both anti-apoptotic bcl-2 and pro-apoptotic bax contribute to mammary apoptosis as well the bcl-2 gene is overexpressed in breast cancer cells." (PMID 24143895, 2013). "The overexpression of Bcl2 has been found in numerous types of cancer, including breast cancer, prostate cancer, B-cell lymphoma and colorectal adenocarcinoma." (PMID 23599765, 2013). "TQ also inhibited the protein expression of anti-apoptotic genes, such as XIAP, survivin, Bcl-xL and Bcl-2, in breast cancer cells and breast tumor xenograft." (PMID 24098377, 2013). "The inhibition of STAT3 by LLL12 also down-regulated the expression of several known STAT3-regulated genes in breast cancer stem-like cells such as Cyclin D1, survivin, Bcl-2, Bcl-XL and an IL-6 regulated gene, Notch1." (PMID 24376586, 2013). "EGFR expression was reported to be an independently worse prognostic factor for breast cancer, whereas Bcl-2 expression is known to be a favorable prognostic factor for breast cancer." (PMID 24245483, 2013). "Inhibition of BCL-2 expression has also been reported to elevate Beclin 1 levels and result in the death of breast cancer cells." (PMID 23840208, 2013). "Similar effects of Tob1 on Bax and Bcl-2 expression in human breast cancer cells have been reported earlier." (PMID 22710759, 2012). "This was particularly evident for Bcl-xL that is about ten time more efficient than Bcl-2 in preventing doxorubicin induced apoptosis in MCF-7 breast cancer cell lines." (PMID 22928777, 2012). "Our results showed that As2O3 suppressed the expression of NF-κB and Bcl-2 both at the mRNA and protein levels in three breast cancer cells." (PMID 22949821, 2012). "Others have shown that in vitro treatment with I3C or DIM inhibits NFκB activity in human breast and prostate cancer cells undergoing apoptosis and reduces BCL-2 mRNA and protein expression in breast cancer cells." (PMID 22514694, 2012). "Consistently, GSIXII treatment combined with Bcl-2/Bcl-xL inhibition by ABT-737 potently enhanced the proapoptotic response of the breast cancer cells, including in ex vivo specimens." (PMID 22703841, 2012). "Higher levels of BCL2 expression in breast tumours have been shown to be an independent prognostic factor for improved survival from breast cancer." (PMID 23961365, 2012). "Our data are consistent with previous observations that BCL2 is a strong independent prognostic marker for breast cancer survival." (PMID 23961365, 2012). "This compound was found to significantly inhibit the proliferation of MCF-7 human breast cancer cells among other cancer cell lines through dysregulation of Bax/Bcl-2 ratio and the induction of G0/G1 cell cycle arrest via inactivation of ERK1/2." (PMID 22997533, 2012). "The product of lipoxygenase-12, 12-hydroxy eicosatetraenoic acid (12-HETE) displayed mitogenic properties in breast cancer cells and its blockade by inhibitors resulted in downregulation of Bcl2, release of cytochrome c and activation of caspases." (PMID 23091604, 2012). "Another report shows that NF-κB induced the resistance of breast cancer by increasing the expression of anti-apoptotic protein Bcl-2 and decreasing the expression of pro-apoptotic protein Bax." (PMID 22159556, 2012).
breast carcinoma (continued). "In this study, we thus specifically addressed the biologic consequences of targeting γ-secretase and Bcl-2/Bcl-xL, alone or simultaneously, in breast cancer cell lines as well as in a novel human breast cancer ex vivo assay." (PMID 22703841, 2012). "In the present study, we show that withanolides inhibited the constitutive activation of NF-κB in MDA-MB-231, an ER-negative human breast cancer cell line, and reduced the anti-apoptotic proteins (Bcl-2, Bcl-xL, and c-FLIP) which are regulated by NF-κB." (PMID 22701533, 2012). "A previous publication reported that E2 can down-regulate miR-21 expression and thus increases the protein expression of miR-21 target genes programmed cell death 4 (PDCD4), PTEN and Bcl-2 in MCF-7 breast cancer cells." (PMID 22200848, 2012). "In breast cancer, Bcl-2 levels correlate with ER-positivity, as the expression of BCL2 is transcriptionally regulated by ERα." (PMID 22343619, 2012). "The role of miR-195 in suppression of anti-apoptotic BCL-2 lends support to the evidence that miR-195 is down-regulated in breast cancer, promoting cell survival." (PMID 23335942, 2012). "T47D is another estrogen responsive ERα positive breast cancer cell line which is used to examine the expression of bcl-2, cyclinD1 and survivin in response to E2 treatment." (PMID 22260523, 2012). "This compound is also found to induce antiproliferative effects in the breast carcinoma cells, exerts apoptosis through Caspase 3 activation in He La cells, and modulates the Bax/Bcl-2 ratio in liver cancer cells." (PMID 27429805, 2011). "Further, Bcl2 is an independent indicator of a favorable prognosis for all types of early-stage breast cancer." (PMID 22114675, 2011). "Positive bcl-2 status was a significant positive prognostic factor for breast cancer-specific survival." (PMID 21835023, 2011). "ER has been shown to activate genes associated with proliferation (for example, Cyclin D1) and with anti-apoptosis (for example, Bcl2 and survivin) in breast cancer cells." (PMID 22123186, 2011). "Although Mule, an E3 ligase that targets Mcl-1 for degradation was expressed in mammary epithelial and breast cancer cell lines, rapid increase of polyubiquitinated Mcl-1 and Bcl-2 was detected only in mammary epithelial cells." (PMID 21730980, 2011). "In breast cancer cells, reduced ubiquitination and degradation of Mcl-1 and Bcl-2 was detected with CHX treatment." (PMID 21730980, 2011). "Since Bcl-2 protein has been demonstrated to be correlated with treatment outcomes and prognosis of breast cancer, it is of great significance to find the function pattern of this polymorphism and the possible association with Bcl-2 expression." (PMID 21457555, 2011). "Brain metastases have been found to be associated with HR-negative and triple-negative (ER-, PgR-, HER2-) breast cancers, EGFR expression, low Bcl-2, and breast cancer HER2 expression and presence of HER2 amplification." (PMID 21914172, 2011). "Most breast cancers arise from epithelial cells that express Bcl-2, Bcl-xL and Mcl-1, and enhanced expression of these proteins is almost systematically found in transformed mammary epithelial cells." (PMID 21899728, 2011). "We next examined the key players or mechanisms that increased the ubiquitination and degradation of Mcl-1 and Bcl-2 in mammary epithelial cells as well as their aberrations in breast cancer cells." (PMID 21730980, 2011). "While breast cancer cells were resistant to de novo inhibition of protein synthesis, a rapid proteosome-mediated degradation of Mcl-1 and Bcl-2 induced apoptosis in mammary epithelial cells." (PMID 21730980, 2011). "GST induced apoptosis with alterations of Bax and Bcl-2 levels and increase in caspase-3 activity in human breast cancer MDA-MB-231 cells." (PMID 21822457, 2011). "In this study, we found that increased stability of anti-apoptotic proteins like Mcl-1 and Bcl-2 rendered breast cancer cells resistant to CHX-induced apoptosis." (PMID 21730980, 2011).
breast carcinoma (continued). "Upon nicotine-induced EGFR activation, Src, Akt and ERK1/2 were phosphorylated in MCF10 and MDA-MB-231 breast cancer cells, leading to the upregulation of E2F-1, Bcl-2 expression, and long-term cell survival." (PMID 22085699, 2011). "Recent reports showed that GST switched Bcl-2 from an anti-apoptotic protein into a pro-apoptotic protein in breast cancer cells and increased Bax and decreased Bcl-2 leading to an increase in Bax : Bcl-2 ratio for apoptosis in SK-N-MC cells." (PMID 21822457, 2011). "On the other hand, GST induced alterations in Bax and Bcl-2 levels in breast cancer and neuroblastoma cells." (PMID 21822457, 2011). "C-terminal region of HER4 binds to and antagonizes anti-apoptotic protein Bcl-2 and thereby promotes apoptosis of breast cancer cells." (PMID 21388543, 2011). "Our study also demonstrated that Akt was involved in the regulation of Bcl-2 expression and responsible for the long-term survival of the breast cancer cells." (PMID 22085699, 2011). "This is in accordance with previous findings that SFN induces cell type-specific apoptosis in breast cancer cells with activation of Bax/Bcl-2 and caspases." (PMID 20625516, 2010). "BCL2 suppresses apoptosis via the intrinsic pathway, and thus regulation of BCL2 is a plausible mechanism for the anti-apoptotic function of MYB in mammary carcinoma cells." (PMID 20659323, 2010). "Similar to these findings, we only observed negligible apoptosis in breast cancer cells, although the Bcl-2 level was downregulated by the IKKε siRNA." (PMID 20863366, 2010). "Since this discovery, overexpression of BCL2 protein has been identified in a variety of solid organ malignancies, including breast cancer." (PMID 20664598, 2010). "The expression of BCL-2 in breast cancer tissues with axillary lymph node metastasis were significantly lower than that without lymph node metastasis." (PMID 20691103, 2010). "In this study MTT assay was used to analyze the relative inhibition effect of four kinds of chemotherapy drugs which include EADM, 5-Fu, NVB and DDP on breast cancer cells, and the relationship between the expression of BCL-2, BAD and the chemosensitivity." (PMID 20691103, 2010). "SKBR3, a known low Bcl-2 expressing breast cancer cell line Bcl-2 had an AQUA score of 18, whereas MCF7 and BT474 that are high Bcl-2 expressers showed the highest AQUA scores for Bcl-2 expression." (PMID 20459695, 2010). "The expression rates of BCL-2 were normal breast tissue(90%), breast fibroadenoma(80%) and breast carcinoma(61.25%)." (PMID 20691103, 2010). "In summary, this large analysis establishes BCL2 as an independent and powerful prognostic protein marker in early-stage breast cancer." (PMID 20664598, 2010). "Compare with the other 2 groups, the expression of BCL-2 was higher in breast carcinoma group, the differences were statistically significant(P < 0.05)." (PMID 20691103, 2010). "Antisense oligonucleotide of BCL-2 as an enhancer of the chemotherapeutic effect, provided us a new way for the treatment of breast cancer." (PMID 20691103, 2010). "Bcl-2 expression and prognosis has been correlated for breast cancer patients even if treated with chemotherapy." (PMID 21304176, 2010). "In breast cancer histologic grade I to III the expression of BCL-2 assumed the decreasing tendency, the differences had significant difference, the expresses of BAD during this process also gradually reduced." (PMID 20691103, 2010). "Previous studies from our laboratory demonstrated that decreased expression of NM23-H1 in MCF-7 breast cancer cells enhances expression of Cathepsin D and Bcl2, which are involved in limiting apoptosis, promoting cell migration and increasing angiogenesis." (PMID 20064251, 2010). "BCL2 is an independent indicator of favourable prognosis for all types of early-stage breast cancer." (PMID 20664598, 2010).
breast carcinoma (continued). "It has been reported that the bcl-2 gene is expressed in breast cancer cells, and the level of expression varies with alteration of some apoptotic stimuli." (PMID 20441573, 2010). "The breast cancer cells in which BCL-2 and BAD are all positive are more chemosensitive to NVB than the BCL-2(+)BAD(-)ones(P < 0.05)." (PMID 20691103, 2010). "The ability of BPA to alter the expression of Bcl-2 and Bcl-xL suggests a potential mechanism by which it confers chemoresistance in the two breast cancer cell lines." (PMID 19270784, 2009). "BER reduced the Bcl-2 protein expressions and enhanced the Bax protein expressions in the human breast cancer cells." (PMID 19796390, 2009). "Higher Bax/Bcl-2 ratio predicts good response for chemotherapy in breast cancers, indicating apoptosis." (PMID 21556249, 2009). "Bcl-2 is expressed in 70% of breast cancers and it functions directly in apoptosis regulation and in oncogenesis." (PMID 18454859, 2008). "In studies of human colon cancer and breast cancer increased Bcl-2 expression correlated with prolonged survival." (PMID 18382684, 2008). "Here, we present the results of a meta-analysis of the association between BCL2 expression and both disease free survival (DFS) and overall survival (OS) in female breast cancer." (PMID 18510726, 2008). "To this end, we identified all published reports that assessed the relationship between BCL2 and outcome in breast cancer and performed a meta-analysis using standard statistical techniques." (PMID 18510726, 2008). "A previous immunohistochemistry study suggested that Bcl2 is an independent predictor of breast cancer outcome." (PMID 18928543, 2008). "Antisense to Bcl-2 has activity in breast cancer in preclinical models as a single agent and also sensitizes high Bcl-2-expressing cells to a range of chemotherapeutic agents." (PMID 18430249, 2008). "After a short term (48 hours) induction of HER2 in MCF7 breast cancer cells anti-apoptotic proteins survivin and Bcl-2 are up-regulated." (PMID 18454859, 2008). "On the other hand, in other tumor types, there is an inverse relationship between positive bcl-2 expression and prognosis, such as in prostate cancer, ovarian cancer, non-small cell lung cancer, follicular thyroid cancer, neuroblastoma, and breast cancer." (PMID 18570663, 2008). "A number of prior studies have assessed the prognostic value of the anti-apoptotic mediator Bcl-2 in breast cancer." (PMID 18430249, 2008). "Treatment of ERα(+) breast cancer cells and tissue with E2 led to stimulated growth and up-regulated Bcl-2 expression; however, these carcinogenic effects were diminished by either CLA or Tam and were suppressed further by the combination of CLA and Tam." (PMID 18652667, 2008). "In many solid organ tumours, including breast cancer, BCL2 paradoxically appears to exert a tumour suppressor effect, where its expression is associated with favourable prognostic features e.g. low grade, oestrogen receptor (ER)-positivity and good outcome." (PMID 18510726, 2008). "In some types of neoplasms originating from these tissues (such as lymph nodes with breast cancer metastasis), a relationship between bcl-2 expression and longer disease-free survival has been observed." (PMID 18570663, 2008). "The aim of this study was to evaluate the prognostic role of BCL2 in breast cancer by sytematically reviewing the available evidence." (PMID 18510726, 2008). "There have been many studies reporting that Bcl-2, an apoptosis inhibitor, shows a positive correlation with hormone receptors in breast cancer tissues and is a favorable prognostic factor." (PMID 18837981, 2008). "Most of the literature, however, supports an anti-apoptotic role of Bcl-2 and Bag-1 in early-stage breast cancer, which appears to be related to the transcriptional function of ER." (PMID 18430249, 2008).